TRPV1 (transient receptor potential cation channel subfamily V member 1)
Diseases named in the same sentence as TRPV1 in open-access papers (continued):
Sharing a sentence is not in itself a finding about the gene and the disease.
ovarian carcinoma (7 papers, 2015 to 2025). A malignant neoplasm originating from the surface ovarian epithelium. "Moreover, we analyzed data from TCGA (The Cancer Genome Atlas) and GEO (Gene Expression Omnibus; GSE14407) for ovarian cancer to assess whether TRPV1 expression is associated with prognosis and survival of ovarian cancer patients." (PMID 32604833, 2020). "In ovarian carcinoma, TRPV1 expression is increased compared to normal control or borderline lesions." (PMID 37240443, 2023). "Previously, the association between genetic predisposition of TRPV1 and CIPN was described in a cohort of ovarian cancer patients treated with carboplatin combined with paclitaxel or docetaxel." (PMID 36672910, 2023). "In the present study, we found that the TRPV1 agonist capsaicin has little cytotoxic activity in most cancer cells including ovarian cancer cells." (PMID 32604833, 2020). "In the present study, we introduced the anti-cancer activity of TRPV1 antagonists in human ovarian cancer cells." (PMID 32604833, 2020). "As expected, capsaicin, the TRPV1 agonist, induced calcium influx in ovarian cancer cells, and DWP05195 reversed the influx." (PMID 32604833, 2020). "We observed that TRPV1 is expressed in immortalized ovarian epithelial cells (IOSE80PC) and human ovarian cancer cells." (PMID 32604833, 2020). "In the present study, we investigated the anti-cancer activity of a novel TRPV1 antagonist, DWP05195, and evaluated its molecular mechanism in human ovarian cancer cells." (PMID 32604833, 2020). "Considering that TRPV1 is redox-sensitive, there is a possibility that ROS induced by DWP05195 may counteract the antagonist effect of DWP05195 in the ovarian cancer cells." (PMID 32604833, 2020). "Thus, we examined whether the novel TRPV1 antagonist, DWP05195, also induces ER stress in human ovarian cancer cells." (PMID 32604833, 2020).
periodontitis (7 papers, 2015 to 2026). An acute or chronic inflammatory process that affects the tissues that surround and support the teeth. "The resulting localized ablation of TRPV1 + afferents decreased bone loss in a mouse model of periodontitis, which is in contrast to the results obtained by the systemic injection of vanilloids." (PMID 38455874, 2024). "For example, the oral administration of capsaicin suppressed bone loss in a rodent periodontitis model, which was interpreted as having a protective role for TRPV1 + afferents." (PMID 38455874, 2024). "Continuous functional silencing of TRPV1-expressing neurons after the induction of experimental periodontitis prevented the progression of bone loss in a mouse model of periodontitis." (PMID 38455874, 2024). "Recently, we showed that chemical ablation of nociceptors by resiniferatoxin (RTX) or chemogenetic silencing of TRPV1-lineage afferents reduced bone loss in a periodontitis mouse model." (PMID 37122730, 2023). "In this study we found that Trpv1−/− mice developed severe bone loss in an experimental model of periodontitis." (PMID 27388773, 2016). "Moreover, the upregulation of TRPV1 is associated with many inflammatory diseases, including periodontitis." (PMID 35911651, 2022). "Our study suggests that the TRPV1 channel could be a potential therapeutic target for diseases associated with inflammatory bone resorption, including periodontitis." (PMID 27388773, 2016). "Although TRPV1-expressing afferents magnify alveolar bone remodeling in a periodontitis model, it is important to note that the contribution of nociceptive afferents to alveolar bone remodeling is context-dependent." (PMID 38455874, 2024). "In our study, the TRPV1 agonist CPS was injected into the periodontal tissue of experimental periodontitis rats, and the level of inflammatory mediators in the tissue was increased, along with periodontal attachment loss." (PMID 35911651, 2022). "At the same time, the relationship between TRPV1 expression and clinicopathological features in patients with periodontitis needs to be studied in more clinical samples." (PMID 35911651, 2022). "Due to the complexity and diversity of periodontitis, the expression level and biological functions of TRPV1 need to be verified in other periodontal tissue cells." (PMID 35911651, 2022). "The mechanism by which TRPV1 regulates periodontitis was further verified by injecting the TRPV1 agonist capsaicin (CPS) and antagonist capsazepine (CPZ) into the gingiva of rats; the alveolar bone losses in each group were measured by stereomicroscopy." (PMID 35911651, 2022). "TRPV1 was involved in the process of alveolar bone defects and the inflammatory response in rats with periodontitis induced by ligation." (PMID 35911651, 2022). "An in-depth study of TRPV1 has prospective and guiding effectiveness for the treatment and prognosis of periodontitis patients." (PMID 35911651, 2022). "In this study we demonstrated that TRPV1 activation in gingival nerves evokes the local release of neuropeptide CGRP, which suppresses alveolar bone loss in the ligature-induced periodontitis murine model." (PMID 27388773, 2016). "In this study we addressed the role of the neuronal TRPV1-CGRP signaling axis in the pathogenesis of periodontitis." (PMID 27388773, 2016). "We assessed if ligature-induced periodontitis produces changes in SP or TRPV1 expression in TG." (PMID 37122730, 2023). "Using models of periodontitis in vitro and in vivo, we tested the hypothesis that TRPV1 was upregulated under periodontal inflammatory conditions." (PMID 35911651, 2022). "Accordingly, TRPV1 has the potential to become a new therapeutic target for periodontitis; inhibition of TRPV1 gene activity may become a new and biological-based treatment for periodontitis, which has broad potential for clinical management of periodontitis." (PMID 35911651, 2022).
periodontitis (continued). "Therefore, whether TRPV1 can be used as a drug target and an essential auxiliary means of periodontitis treatment is an essential research direction." (PMID 35911651, 2022). "In both in vivo and in vitro inflammatory modeling environments, the expression of TRPV1 was identically increased, suggesting that TRPV1 might positively affect periodontal inflammation and become a new therapeutic target for inflammatory diseases such as periodontitis." (PMID 35911651, 2022). "Our study identified a functional link between TRPV1 and CGRP, and demonstrated their pathophysiological interaction in an experimental periodontitis model." (PMID 27388773, 2016). "Nonetheless, given the modest extent of changes, we presume that altered expressions of SP or TRPV1 in gingival afferents are not major contributors to the nociceptor regulation of periodontitis." (PMID 37122730, 2023). "In vitro experiments showed that LPS induced the upregulation of TRPV1 and proinflammatory cytokines and promoted the phosphorylation of PI3K and AKT proteins in HPDLCs, which was consistent with their expression in the rat periodontitis model." (PMID 35911651, 2022). "Therefore, it is possible that periodontitis-induced TRPV1/TRPA1 signaling triggers SP secretion from nociceptors in ligature-induced periodontists." (PMID 37122730, 2023). "Upstream events leading to upregulation of TRPV1 in periodontitis were not investigated." (PMID 35911651, 2022). "Collectively, these results led us to propose a working model in which the activation of TRPV1-expressing sensory neurons in gingiva induces local CGRP secretion, which in turn suppresses osteoclastogenesis under inflammatory conditions as occurring in periodontitis." (PMID 27388773, 2016). "Moreover, the expression of TRPV1 and TLR4 found in keratinocytes, fibroblasts, inflammatory cells and capillary endothelial cells in patients with aggressive and chronic periodontitis suggests a role for TRPV1 signaling in the induction of the NLRP3 inflammasome." (PMID 25644504, 2015). "It was preliminarily proven that TRPV1 might regulate inflammatory factors through the PI3K/AKT pathway, thereby affecting the occurrence and progression of bone destruction and providing new approaches to the diagnosis and treatment of patients with periodontitis." (PMID 35911651, 2022). "Interestingly, the ablation of TRPV1-expressing trigeminal nociceptors did not alter the periodontal microbiome within the ligature, suggesting TRPV1-expressing afferents enhance bone destruction in periodontitis by promoting hyperactive host responses in the periodontium." (PMID 38455874, 2024).
rosacea (7 papers, 2018 to 2025). A chronic erythematous skin disorder that affects the face. "Niacin, or vitamin B3, found in foods such as liver, tuna, and peanuts, activates TRPV1 channels and niacin receptors, causing flushing and potentially worsening rosacea." (PMID 40149947, 2025). "In addition, we made an in vitro model of rosacea to mimic and environment of increased Trpv1 mRNA caused by UVB or heat exposure to F11 cells, which are sensory neuronal cells." (PMID 33800730, 2021). "Rosacea is associated with a microbiome dysbiosis with increase in Demodex mites and expression of transient receptor potential cation channel subfamily V member 1 TRPV1, tropomyosin receptor kinase A (TrkA) and nerve growth factor (NGF), triggering cutaneous neurogenic inflammation." (PMID 38899754, 2024). "Among the most well-documented dietary triggers, hot foods and beverages can exacerbate rosacea symptoms by inducing vasodilatation and stimulating transient receptor potential vanilloid member 1 (TRPV1) channels." (PMID 40149947, 2025). "Substantial efforts have been made to elucidate the role of TRPV1 in the inflammatory stage of rosacea." (PMID 36874007, 2023). "TRPV1 expression level on skin biopsy was reported to be higher in patients with erythematotelangiectatic and phymatous rosacea than in healthy controls." (PMID 33800730, 2021). "Some studies have revealed that TRPV1 antagonists have certain antidepressant and antianxiety effects, which may be beneficial to rosacea patients as they often suffer from psychological stress." (PMID 36874007, 2023). "Furthermore, coactivation of TRPV1 and TRPA1 channels induces chronic inflammatory skin disease such as rosacea, which is associated with neurogenic inflammation." (PMID 35058918, 2021). "Therefore, TRPV1 may be a new therapeutic target for rosacea." (PMID 36874007, 2023). "A study has shown significantly increased expression of TRPV1 on non-neuronal cells in rosacea patients with erythema telangiectasia." (PMID 36874007, 2023). "Studies that showed reduction in burning sensation in rosacea with a TRPV1 antagonist are not many." (PMID 33800730, 2021).
schizophrenia (7 papers, 2011 to 2025). A major psychotic disorder characterized by abnormalities in the perception or expression of reality. "There was a temporary deficiency in the investigation of the alterations in TRPV1 expression and oxidative stress levels within both central and peripheral systems in patients with schizophrenia." (PMID 40309794, 2025). "However, this feedback mechanism is insufficient to counteract the intrinsic downregulation of TRPV1 associated with schizophrenia progression." (PMID 40309794, 2025). "In addition, some animal studies have explored the association between TRPV1 and schizophrenia-like behavior." (PMID 37935716, 2023). "In addition, TRPV1 has been linked to pain perception and cognition deficits in schizophrenia." (PMID 28680405, 2017). "Preclinical maternal separation (MS) models recapitulate schizophrenia-like behavioral and synaptic deficits, paralleled by hippocampal microglial TRPV1 downregulation." (PMID 40931576, 2025). "Our work identifies microglia-specific TRPV1 modulation as a new therapeutic strategy for schizophrenia, highlighting its therapeutic potential for cognitive and negative symptoms in schizophrenia." (PMID 40931576, 2025). "The aim of this study is to further explore schizophrenia biomarkers by analyzing TRPV1 and oxidative stress in astrocyte-derived extracellular vesicles (ADEs) and peripheral blood mononuclear cells (PBMCs)." (PMID 40309794, 2025). "A previous study found a decrease in TRPV1 expression in a schizophrenic rat model, and similar findings have been found in patients with schizophrenia." (PMID 40309794, 2025). "Administration of TRPV1 agonist CAP (50 mg/kg s.c.)on day 2 of life resulted in hyperactive schizophrenia-like behavior at weeks 5–7, but increased PPI at weeks 8-1249." (PMID 37935716, 2023). "Consistent with previous results, our study also showed that the use of TRPV1 agonists improved cognition and other schizophrenia-like behavior." (PMID 37935716, 2023). "ABT-239 is a histamine H3 receptor antagonist and transient vanilloid receptor type 1 (TRPV1) antagonist proposed for the treatment of schizophrenia and attention-deficit/hyperactivity disorder (ADHD)." (PMID 38140657, 2023). "Rodent studies so far have only provided indirect relationships between TRPV1 and schizophrenia symptoms." (PMID 28680405, 2017). "Therefore, the primary aim of this study is to examine alterations in TRPV1 expression and oxidative stress levels in ADEs and peripheral blood mononuclear cells (PBMCs) from patients with schizophrenia." (PMID 40309794, 2025). "Our prior clinical findings revealed significantly reduced transient receptor potential vanilloid 1 (TRPV1) expression in both first-episode and recurrent schizophrenia patients, with levels inversely correlating with symptom severity, implicating TRPV1 dysfunction in disease progression." (PMID 40931576, 2025). "Moreover, this study exclusively utilized a cross-sectional design, and this is insufficient to capture the roles of TRPV1 and oxidative stress responses in schizophrenia pathogenesis." (PMID 40309794, 2025). "It was indicated that TRPV1 could be a biomarker for schizophrenia and reflect the disease severity." (PMID 40309794, 2025). "A correlation analysis with the clinical symptoms indicated a negative association between TRPV1 expression in the PBMCs and ADEs of patients with schizophrenia and negative symptoms." (PMID 40309794, 2025). "TRPV1 expression was markedly reduced in patients with schizophrenia." (PMID 40309794, 2025). "In recent years, much literature has provided evidence that TRPV1 may play an important role in the development of schizophrenia." (PMID 37935716, 2023). "Some studies have shown that TRPV1 induces or exacerbates schizophrenia-like behaviors." (PMID 37935716, 2023). "Thus, an interesting approach would be to electrophysiologically probe the VTA-mPFC communication under TRPV1 agonists (e.g., capsaicin) in schizophrenia models." (PMID 28680405, 2017).
schizophrenia (continued). "However, other studies suggested that TRPV1 activation reduces schizophrenia-like behaviors." (PMID 37935716, 2023). "An analysis of TRPV1, Sirt3, SOD2, and acetyl-SOD2 in the PBMCs and ADEs of the patients with schizophrenia showed that TRPV1 in the PBMCs exhibited a positive correlation with that in the ADEs." (PMID 40309794, 2025). "In particular, Type III Nrg1 back signaling can acutely activate PtdIns3K along sensory neuron axons making TRPV1 a potential molecular link between Type III Nrg1, schizophrenia and alterations in pain sensation." (PMID 21949864, 2011). "In this study, the detection of ADEs revealed that, similar to the findings in PBMCs, the TRPV1 and Sirt3 expressions were significantly downregulated, while the SOD2 and acetyl-SOD2 expressions were significantly increased in patients with schizophrenia compared with those of the HC group." (PMID 40309794, 2025). "Given that abnormal motor-evoked potentials and pain sensitivity are observed in schizophrenia patients, TRPV1 channels—and therefore the endovanilloid system—could be altered in schizophrenia, which deserves neurophysiological investigation." (PMID 28680405, 2017).
squamous cell carcinoma (7 papers, 2014 to 2025). A carcinoma arising from squamous epithelial cells. "This analysis showed that TRPV1 mRNA expression was significantly increased in squamous cell carcinoma (LUSC) and adenocarcinoma (LUAD)." (PMID 35402237, 2022). "Similarly, elevated TRPV1 mRNA levels in lung adenocarcinoma and squamous cell carcinoma tissues compared to control tissues suggest a potential role for TRPV1 in tumor progression." (PMID 39407657, 2024). "In vitro, TRPA1 and/or TRPV1 activation has been shown to kill squamous cell carcinoma cells." (PMID 37240443, 2023).
acute pancreatitis (6 papers, 2018 to 2025). An acute inflammatory process that leads to necrosis of the pancreatic parenchyma. "The pancreatitis-associated pain was shown to be related to TRPA1 and TRPV1 expression, and it functioned in afferents in an experimental acute pancreatitis model in mouse." (PMID 30087301, 2018). "It is reported that H2S triggers TRPV1 to mediate chloride secretion in acute pancreatitis and colon." (PMID 30062050, 2018). "TRPV1 activation was also found to be involved in acute pancreatitis." (PMID 30871017, 2019). "Therefore, targeting of TRPA1 and TRPV1 in patients with recurrent bouts of acute pancreatitis may inhibit the progression to chronic pancreatitis." (PMID 30087301, 2018). "Another study highlighted the synergistic role of TRPV1 and TRPA1 in acute pancreatitis development." (PMID 34829924, 2021). "Early intervention with TRPV1 and TRPA1 antagonists (within three weeks of the development of acute pancreatitis) attenuated the transition to and development of CP and downstream pain behaviors in mice." (PMID 34829924, 2021).
airway hyperresponsiveness (6 papers, 2023 to 2025). "Future investigations should explore the bidirectional regulatory networks between PNECs and the nervous and immune systems, particularly focusing on interactions with the vagus nerve and Trpv1+ neurons, and their effects on airway hyperresponsiveness." (PMID 41573715, 2025). "Keyword clustering refined the topic distributions and could be generalized as neuralgia, endogenous cannabinoid system, TRPV1 mediated airway hyperresponsiveness, involvement of apoptosis, TRPV1 antagonists as therapy targets." (PMID 37025492, 2023). "Concurrently, oxidative stress upregulates transient receptor potential vanilloid 1 (TRPV1) and transient receptor potential ankyrin 1 (TRPA1) channels, triggering neurogenic inflammation and airway hyperresponsiveness." (PMID 41450494, 2025). "TNF-α activates TRPV1+ DRG neurons, sensitizing them to TRPV1 activators, leading to airway hyperresponsiveness." (PMID 39185421, 2024).